SLC7A9 (solute carrier family 7 member 9)
Diseases named in the same sentence as SLC7A9 in open-access papers (continued):
Sharing a sentence is not in itself a finding about the gene and the disease.
bladder cancer (1 paper, 2023). "In this study, we established the GMII consisting of eight glutamine metabolism-related genes (ENPP1, GALK1, TALDO1, CYP19A1, FASN, AHCY, SLC7A9, and HSPG2), a high value of which is associated with poor prognosis in bladder cancer patients." (PMID 36911676, 2023). "The expression of five of the eight GMII genes (TALDO1, AHCY, FASN, GALK1 and SLC7A9) in bladder cancer tissues was higher than that in normal tissues, while ENPP1, CYP19A1 and HSPG2 were down-regulated in tumor tissues (p < 0.05)." (PMID 36911676, 2023).
colitis (1 paper, 2024). Inflammation of the colon. "Overall, the findings indicate that the impact of HFD on DSS‐induced colitis may be linked to intestinal dysbiosis and specific genes such as Abca8b, Ace2, Apoa1, Apoa4, Apoc3, Aspa, Dpp4, Maob, Slc34a2, Slc7a9, and Trpm6." (PMID 39479684, 2024). "Impact of HFD on DSS‐induced colitis may be linked to intestinal dysbiosis and specific genes such as Abca8b, Ace2, Apoa1, Apoa4, Apoc3, Aspa, Dpp4, Maob, Slc34a2, Slc7a9, and Trpm6." (PMID 39479684, 2024).
cystine urolithiasis (1 paper, 2020). Urolithiasis in which the composition of the stones is predominantly cystine. "Rare variants on SLC3A1 AND SLC7A9 detected in 13 families with cystine urolithiasis." (PMID 32133030, 2020).
diabetic nephropathy (1 paper, 2020). "Gene Grem1 and Slc7a9 are associated with diabetic nephropathy." (PMID 32523943, 2020).
esophageal squamous cell carcinoma (1 paper, 2024). Esophageal squamous cell carcinoma (ESCC) is a type of esophageal carcinoma (EC) that can affect any part of the esophagus, but is usually located in the upper or middle third. "Conversely, knockdown of SLC7A9 inhibited the migration, invasion, and proliferation of esophageal squamous cell carcinoma cells, making it a suitable biomarker to predict lymph node metastasis of this cancer." (PMID 38244585, 2024).
kidney damage (1 paper, 2014). "The second SNP lies within the SLC7A9 gene, rare mutations of which have been linked to severe kidney damage." (PMID 24586186, 2014). "SLC7A9 is linked to kidney function: rare mutations in SLC7A9 cause severe kidney damage, and a common variant (rs12460876, linked to rs8101881 with r2 = 0.996) is associated with the estimated glomerular filtration rate (eGFR), which is a key clinical measure of kidney health." (PMID 24586186, 2014).
lysinuric protein intolerance (1 paper, 2021). Lysinuric protein intolerance (LPI) is a very rare inherited multisystem condition caused by disturbance in amino acid metabolism. "Indeed, mutations in SLC7A9 (b0,+AT) lead to cystinuria (MIM 220100), whereas mutations in SLC7A7 (y + LAT1) result in lysinuric protein intolerance (LPI) (MIM 222700)." (PMID 34436365, 2021).
nephritis (1 paper, 2016). Inflammation of renal tissue. "The top 5 up-regulated genes based upon fold change between groups were: carbamoyl-phosphate synthase 1 (CPS1), carboxypeptidase O (CPO), tubulointerstitial nephritis antigen (TINAG), solute carrier family 7, member 9 (SLC7A9), and solute carrier family 6, member 19 (SLC6A19)." (PMID 27093613, 2016).
thyroiditis (1 paper, 2018). Inflammation of the thyroid gland. "Thyroiditis was significantly correlated with SLC7A2, SLC7A3, SLC7A7, and SLC7A9." (PMID 30558624, 2018).
cancer (4 papers, 2020 to 2025). A tumor composed of atypical neoplastic, often pleomorphic cells that invade other tissues. "Then, the top five higher binding energy ginsenosides were used for docking with other SLC transporters, including SLC7A5, SLC7A6, LCN2, and SLC7A9 cancer-related targets, as well as BSG due to its involvement in amino acid transport." (PMID 40566559, 2025). "Additionally, an analysis of cancer stages revealed a significant correlation between the expression levels of SLC3A2, BSG, SLC7A5, SLC7A6, LCN2, and SLC7A9 and the pathological stages of ACC, with p-values of 0.28, 0.468, 0.00799, 0.0237, 0.0359, 0.264, 0.193, 0.81, and 0.0246, respectively." (PMID 40566559, 2025). "In addition to these, we also identified some novel genes among the 14-CpG markers that were not previously associated with cancer recurrences such as IFFO1, ALKAL1, FAHD1, FSTL4, SLC7A9, IQCJ-SCHIP1, CLDN11 and three other CpGs at intergenic regions." (PMID 34207933, 2021).
tumor (3 papers, 2023 to 2024). "After 42 days, the mice were euthanised, tumours were collected, and SLC7A9 expression was evaluated by IHC." (PMID 39437660, 2024). "After 63 days, the mice were euthanised, the tumours were collected, and SLC7A9 expression was evaluated by IHC." (PMID 39437660, 2024). "We found that both SLC7A9 knockdown and chemotherapy inhibited tumour growth, and the dual treatment showed the maximum therapeutic effect." (PMID 39437660, 2024). "We found that either SLC7A9 knockdown or erastin treatment inhibited tumour growth, and dual treatment showed the maximum therapeutic effect." (PMID 39437660, 2024). "In addition, propantheline, which can be used to enhance the efficacy of antiretroviral drugs, can target SLC7A9, which in turn affects the amino acid nutrition of the tumor microenvironment and thus tumor cell survival." (PMID 36911676, 2023). "The average immunohistochemistry (IHC) staining score for SLC7A9 expression was significantly higher in tumour tissues than in adjacent non-tumour tissues." (PMID 39437660, 2024).
SLC7A9 also shares sentences with these, for which no sentence is quoted: genetic disorder (3 papers); infection (3); chronic kidney disease (2); Dent disease (2); metabolic disease (2); renal tubular acidosis (2); urolithiasis (2); adrenocortical cancer (1); autosomal dominant tubulointerstitial kidney disease (1); brain cancer (1); colon cancer (1); colorectal cancer (1); cystic fibrosis (1); cystinuria type A (1); cystitis (1); dilated cardiomyopathy (1); esophageal cancer (1); familial Mediterranean fever (1); Fanconi syndrome (1); gallbladder cancer (1); Hartnup disease (1); Hepatic steatosis (1); Hyperammonemia (1); Hypercalciuria (1); hyperlipidemia (1); hypophosphatemic rickets (1); iminoglycinuria (1); ischemic stroke (1); kidney cancer (1); liver cancer (1).
A further 13 diseases each share a sentence with SLC7A9 in 1 paper.